ZCCHC8 (zinc finger CCHC-type containing 8)
Description:
Scaffolding subunit of the trimeric nuclear exosome targeting (NEXT) complex that is involved in the surveillance and turnover of aberrant transcripts and non-coding RNAs. NEXT functions as an RNA exosome cofactor that directs a subset of non-coding short-lived RNAs for exosomal degradation. May be involved in pre-mRNA splicing (Probable). It is required for 3'-end maturation of telomerase RNA component (TERC), TERC 3'-end targeting to the nuclear RNA exosome, and for telomerase function.
Synonyms: DKFZp434E2220; PFBMFT5
Tractability: Small molecule: a structure with a bound ligand is known. PROTAC: UniProt records ubiquitination sites on it; ubiquitination databases record sites on it; its protein half-life has been measured.
Gene: Protein-coding gene on chromosome 12 (122,471,600 to 122,500,932, reverse strand). Ensembl gene ENSG00000033030.
Subcellular location: Nucleus, nucleoplasm; Nucleus
Subcellular location (Human Protein Atlas): Nucleoplasm
Pathways (Reactome):
Gene expression (Transcription): Regulation of endogenous retroelements by the Human Silencing Hub (HUSH) complex
Metabolism of RNA: Nuclear RNA decay
Gene Ontology:
Molecular function: protein binding; RNA binding; nucleic acid binding; zinc ion binding
Biological process: co-transcriptional lncRNA 3' end processing, cleavage and polyadenylation pathway; mRNA 3'-end processing; mRNA splicing, via spliceosome; RNA catabolic process; RNA processing; snRNA catabolic process
Cellular component: catalytic step 2 spliceosome; nuclear exosome targeting complex; nucleolus; nucleoplasm; nucleus; TRAMP complex
Genetic constraint (gnomAD): Loss-of-function variants: 26 observed, 50.88 expected, observed/expected ratio (o/e) 0.51, 90% interval 0.37 to 0.71. The upper end of that interval is the gene's LOEUF score, 0.71, which puts it in group 2 of 6, group 1 being the genes least tolerant of losing a copy. Missense variants: 674 observed, 753.79 expected, observed/expected ratio (o/e) 0.89, 90% interval 0.84 to 0.95. Synonymous variants: 269 observed, 273.63 expected, observed/expected ratio (o/e) 0.98, 90% interval 0.89 to 1.09.
Gene-disease validity (ClinGen):
ClinGen rates the evidence that ZCCHC8 causes each of these diseases.
pulmonary fibrosis and/or bone marrow failure, telomere-related, 5 (autosomal dominant): Moderate. A disease associated with shortened telomeres.
Homologues: Orthologues: chimpanzee ZCCHC8 (99% identical), macaque ZCCHC8 (96% identical), dog ZCCHC8 (88% identical), rabbit ZCCHC8 (86% identical), pig ZCCHC8 (82% identical), guinea pig ZCCHC8 (81% identical), rat Zcchc8 (81% identical), mouse Zcchc8 (81% identical), tropical clawed frog zcchc8 (58% identical), zebrafish zcchc8 (47% identical), Drosophila melanogaster CG4622 (22% identical), Caenorhabditis elegans ZK632.11 (17% identical), and 1 more.
Diseases named in the same sentence as ZCCHC8 in open-access papers:
ZCCHC8 is named in the same sentence as 19 diseases in open-access papers, as found by Europe PMC text mining. Sharing a sentence is not in itself a finding about the gene and the disease. The quoted sentences say what the papers report.
pulmonary fibrosis (3 papers, 2024 to 2025). Chronic progressive interstitial lung disorder characterized by the replacement of the lung tissue by connective tissue, leading to progressive dyspnea, respiratory failure, or right heart failure. "Previously, a monoallelic missense variant in ZCCHC8 (p.Pro186Leu) was documented to co-segregate with low levels of mature TERC in a single family, where individuals exhibited short telomeres, pulmonary fibrosis, or bone marrow failure." (PMID 39198715, 2024).
bone marrow failure syndrome (1 paper, 2024). "At present, only two mutations of ZCCHC8 were reported in three families with IPF and/or bone marrow failure syndrome." (PMID 39256642, 2024).
brain tumor (1 paper, 2022). "We hypothesized that ZCCHC8, as a 5′ fusion partner, might drive (over)expression of the ROS1 transcript and compared the ROS1 expression with that of all other brain tumor samples in our cohort." (PMID 35085008, 2022).
chronic obstructive lung disease (1 paper, 2024). "A novel mutation (NM_017612: c.1228 C > G/p.P410A) of ZCCHC8 was identified in a Chinese family with IPF and chronic obstructive lung disease (COPD)." (PMID 39256642, 2024). "Among these 124 patients, a novel mutation (NM_017612: c.1228 C > G/p.P410A) of Zinc Finger CCHC-Type Containing 8 (ZCCHC8)was identified in a family with IPF and chronic obstructive lung disease." (PMID 39256642, 2024).
Hydrocephalus (1 paper, 2022). Hydrocephalus is an active distension of the ventricular system of the brain resulting from inadequate passage of CSF from its point of production within the cerebral ventricles to its point of absorption into the systemic circulation. "In addition to having similar genomic features that are associated with high mutation rates, adult mice lacking zinc finger CCHC domain-containing protein 8 (ZCCHC8) develop hydrocephalus." (PMID 36406122, 2022).
interstitial lung disease (1 paper, 2024). A diverse group of lung diseases that affect the lung parenchyma. "In summary, by analyzing the whole exome sequencing data of 124 patients with interstitial lung disease, we identified a novel mutation (NM_017612: c.1228 C > G/p.P410A) of ZCCHC8 in a Chinese family with IPF and COPD." (PMID 39256642, 2024).
neuroblastoma (1 paper, 2010). Neuroblastoma (NB) is the most common solid, extracranial childhood tumor. "Using the in silico data mining approach, we identified elevated expression of five genes located at the 12q24.31 amplicon in neuroblastoma (DIABLO, ZCCHC8, RSRC2, KNTC1 and MPHOSPH9)." (PMID 20444257, 2010). "In addition to DIABLO, also ZCCHC8, RSRC2, KNTC1 and MPHOSPH9 showed statistically increased expression in neuroblastoma samples when compared to the groups of healthy samples." (PMID 20444257, 2010).
Obesity (1 paper, 2018). Accumulation of substantial excess body fat. "Instead, our screen suggests that different nearby cis gene may be more fruitful for further functional follow up for obesity, namely ZCCHC8, VPS33A, RSRC2; SPDEF, NUDT3; SETD1, VKORC1; SGSM2, SRR; VASP, SIX5; OTX1; BANK1; ARIH1; ELL; CHST8, respectively." (PMID 29608557, 2018).
short telomere syndrome (1 paper, 2023). "A genome-wide analysis identified ZCCHC8 mutations in an adult with IPF who exhibited typical features of short telomere syndrome and a family history consistent with autosomal dominant pulmonary fibrosis; 13 affected family members were deceased." (PMID 36860670, 2023). "No ZCCHC8 variants or other short telomere syndrome phenotypes were found in 42 genetically-unidentified families that had also been screened for PF." (PMID 36860670, 2023).
tumor (4 papers, 2023 to 2024). "Six upregulated and mutated tumor antigens related to NMD, and infiltration of APCs were identified in patients with BLCA, including HP1BP3, OSBPL9, SSH3, ZCCHC8, FANCI, and EIF4A2." (PMID 36761744, 2023). "By pair-wise Pearson correlation analysis using GEPIA website tool with tumor data from TCGA database, we found that the mRNA expression level of ZCCHC8 is positively correlate with RBMX level, suggesting that RBMX might regulate TERRA degradation by interacting with ZCCHC8." (PMID 37756323, 2023). "Six rare fusion partners were also identified: GOPC, MPRIP, NUP210L, ZCCHC8, CCDC6, and CFAP53, each present in one tumor." (PMID 38835380, 2024). "Fusion ZCCHC8--RSRC2, previously detected in several tumor studies, was identified as highly prevalent and broadly expressed across cell types in HGSOC Patient-3 tumor and matched normal samples, identified in 46% and 36% of sequenced cells, respectively." (PMID 38464114, 2024). "Six tumor antigens (HP1BP3, OSBPL9, SSH3, ZCCHC8, FANCI and EIF4A2) were correlated with the expression of NMD factors and infiltration of APCs, which may be promising candidates for mRNA vaccines." (PMID 36761744, 2023).
cancer (1 paper, 2022). A tumor composed of atypical neoplastic, often pleomorphic cells that invade other tissues. "FAS, C16orfS4, FBXO31, ACSS3, ZCCHC8 and THBS3 were found to help the metastatic cancer cells survive from the immune surveillance." (PMID 35685372, 2022).
CNS tumors (1 paper, 2024). "Six different ROS1 fusion partners have already been described in pediatric CNS tumors (+/−7% of pediatric CNS tumors): GOPC, ARCN1, CHCHD3, ZCCHC8, TPR and CEP85L." (PMID 39409964, 2024).
infection (1 paper, 2018). The state of being infected such as from the introduction of a foreign agent such as serum, vaccine, antigenic substance or organism. "At 3 days post-infection, cells were transduced with lentiviral particles expressing shRNAs targeting MTR4, ZFC3H1+ZCCHC8 or a negative control shRNA." (PMID 29554134, 2018).
ZCCHC8 also shares sentences with these, for which no sentence is quoted: autism (1 paper); bone marrow failure (1); epilepsy (1); genetic disorder (1); idiopathic pulmonary fibrosis (1); neutropenia (1).